USP54 (ubiquitin specific peptidase 54)
Description:
Deubiquitinase that specifically mediates 'Lys-63'-linked deubiquitination of substrates with a polyubiquitin chain composed of at least 3 ubiquitins. Specifically recognizes ubiquitin chain in position S2 and catalyzes cleavage of polyubiquitin within 'Lys-63'-linked chains. Not able to deubiquitinate substrates with shorter ubiquitin chains. Mediates deubiquitination of PLK4, maintaining PLK4 stability by reducing its ubiquitination-mediated degradation.
Synonyms: C10orf29; FLJ37318; bA137L10.3; bA137L10.4
Tractability: Small molecule: a structure with a bound ligand is known. PROTAC: ubiquitination databases record sites on it.
Gene: Protein-coding gene on chromosome 10 (73,497,538 to 73,626,117, reverse strand). Ensembl gene ENSG00000166348.
Subcellular location (Human Protein Atlas): Mitochondria
Gene Ontology:
Molecular function: cysteine-type deubiquitinase activity; K63-linked deubiquitinase activity; protein binding
Biological process: protein deubiquitination
Genetic constraint (gnomAD): Loss-of-function variants: 87 observed, 177.65 expected, observed/expected ratio (o/e) 0.49, 90% interval 0.41 to 0.58. The synonymous counts are far from expectation, so gnomAD's model fits this gene poorly and the ratio says little. Missense variants: 1,778 observed, 2,146.2 expected, observed/expected ratio (o/e) 0.83, 90% interval 0.8 to 0.86. Synonymous variants: 655 observed, 781.36 expected, observed/expected ratio (o/e) 0.84, 90% interval 0.79 to 0.89.
Homologues: Orthologues: chimpanzee USP54 (99% identical), macaque USP54 (97% identical), dog USP54 (88% identical), rabbit USP54 (87% identical), pig USP54 (85% identical), rat Usp54 (78% identical), guinea pig USP54 (77% identical), mouse Usp54 (76% identical), tropical clawed frog usp54 (52% identical), zebrafish usp54a (44% identical). Paralogues in human: USP53 (22% identical).
Diseases named in the same sentence as USP54 in open-access papers:
USP54 is named in the same sentence as 26 diseases in open-access papers, as found by Europe PMC text mining. Sharing a sentence is not in itself a finding about the gene and the disease. The quoted sentences say what the papers report.
colorectal cancer (4 papers, 2016 to 2024). A primary or metastatic malignant neoplasm that affects the colon or rectum. "By performing carcinogenesis protocols, we have demonstrated the oncogenic relevance of USP54 in colon cancer by finding that Usp54 deficiency protects against chemically-induced colorectal carcinoma." (PMID 27769071, 2016). "For example, USP54 is found to be overexpressed in colorectal cancer, which confers stem-cell-like traits to colorectal cancer cells and facilitates intestinal tumorigenesis." (PMID 38517383, 2024). "USP54 is overexpressed in intestinal stem cells; USP54 downregulation in colorectal carcinoma cells impedes tumorigenesis." (PMID 38321455, 2024). "In this context, we have analyzed the expression profile of several USPs in colorectal cancer stem cells, and we have found that USP54 is consistently upregulated." (PMID 27769071, 2016). "To investigate USP54 role in colorectal cancer development in vivo, we induced colon carcinomas in Usp54+/+ and Usp54KF/KF mice, using azoxymethane (AOM) and dextran sulfate sodium (DSS)." (PMID 27769071, 2016). "Altogether, these data support the role of USP54 in promoting colorectal carcinoma and suggest a new function of USP54 in controlling the stem properties of intestinal cells." (PMID 27769071, 2016). "Here, we show that USP54 is overexpressed in intestinal stem cells and demonstrate that its downregulation in colorectal carcinoma cells impedes tumorigenesis." (PMID 27769071, 2016). "Finally, we show that high levels of USP54 are a poor prognosis marker in colorectal carcinoma, suggesting the interest of this enzyme as a potential target of anticancer therapies." (PMID 27769071, 2016).
colon carcinoma (2 papers, 2016 to 2025). "We have found that USP54 deficiency protects against azoxymethane-induced colon carcinoma and inhibits metastasis formation by melanoma cells, indicating that this DUB functions as an oncogenic factor in both malignancies." (PMID 27769071, 2016). "Furthermore, we show that USP54 is upregulated in human colon cancer and associates with poor prognosis." (PMID 27769071, 2016). "Although USP54 is dispensable for normal mouse survival, as indicated by knockout models, its upregulation in chemically induced colon carcinoma promotes invasion and metastasis." (PMID 40168312, 2025). "In summary, we have demonstrated that USP54 is overexpressed in colon CSCs and promotes both colon carcinoma and melanoma progression." (PMID 27769071, 2016). "Accordingly, we have shown that downregulation of USP54 significantly decreases the tumorigenicity of colon cancer cells." (PMID 27769071, 2016). "To further clarify the relevance of USP54 in colon cancer, we analyzed the expression of this DUB in transcriptional data from colorectal adenomas and normal mucosa (GEO accession GDS2947)." (PMID 27769071, 2016). "In this work, we have demonstrated that USP54 is overexpressed in intestinal cancer stem cells (CSCs) and that its downregulation reduces the tumorigenicity of colon cancer cells both in vitro and in vivo." (PMID 27769071, 2016).
gastric cancer (2 papers, 2024). A primary or metastatic malignant neoplasm involving the stomach. "USP54 promotes gastric cancer progression by deubiquitinating PLK4." (PMID 38321455, 2024). "CEP120/USP54/PLK4 enhances centrosome amplification and gastric cancer advancement." (PMID 39605891, 2024).
leukemia (2 papers, 2016). A malignant (clonal) hematologic disorder, involving hematopoietic stem cells and characterized by the presence of primitive or atypical myeloid or lymphoid cells in the bone marrow and the blood. "This study is the first to confirm that both PTPN21 and USP54 are mutated in human leukemia." (PMID 26527318, 2016). "In addition to gene mutations that are known to be involved in leukemogenesis, such as ones in MYC and KRAS, we also identified mutations within PTPN21, TBX21, USP54, USP11, NCOR2, CSPP1 that have never before been identified in human leukemia." (PMID 26527318, 2016).
adenoma (1 paper, 2016). A neoplasm arising from the epithelium. "We found a significant increase in USP54 expression in adenomas compared to matched normal mucosa." (PMID 27769071, 2016).
colitis (1 paper, 2016). Inflammation of the colon. "Additionally, we measured shortening of colon as a marker of inflammation and found that colon samples from wild-type mice where shorter than those from Usp54-deficient animals, revealing a less severe colitis in the absence of this deubiquitinase." (PMID 27769071, 2016).
esophageal adenocarcinoma (1 paper, 2024). A malignant tumor with glandular differentiation arising predominantly from Barrett mucosa in the lower third of the esophagus. "In esophageal adenocarcinomas, the USP54-encoding gene is sometimes fused with the CAMK2G-encoding gene." (PMID 38321455, 2024).
intestinal cancer (1 paper, 2016). "Moreover, analysis of reported data on survival of patients with intestinal cancer showed a positive correlation between high USP54 expression and lower survival." (PMID 27769071, 2016).
melanoma (1 paper, 2016). A malignant, usually aggressive tumor composed of atypical, neoplastic melanocytes. "Additionally, we have found that Usp54 downregulation impairs experimental lung metastasis formation by melanoma cells, corroborating the pro-tumoral effect of USP54 also in this pathology." (PMID 27769071, 2016). "To further evaluate the role of USP54 in cancer progression, we analyzed in vivo the effect of Usp54 knockdown on the formation of experimental lung metastasis by B16F10 murine melanoma cells." (PMID 27769071, 2016).
metastatic melanoma (1 paper, 2016). A melanoma that has spread from its primary site to another anatomic site. "Collectively, these results support the essentiality of USP54 for lung metastasis formation in vivo, corroborating its oncogenic function in metastatic melanoma progression." (PMID 27769071, 2016).
oral squamous cell carcinoma (1 paper, 2025). "Whilst no DUBs have previously been reported to regulate KIFC1, candidates from genome-wide screens for centrosome clustering regulators in Drosophila or oral squamous cell carcinoma, included orthologs of USP8 (CG5798) and USP43 (CG30421) and the pseudo-DUB USP54." (PMID 39789388, 2025).
prostate carcinoma (1 paper, 2024). A carcinoma that arises from epithelial cells of the prostate gland. "Therefore, understanding the biological function of USP54 in androgen-dependent prostate cancer cells requires further exploration." (PMID 38321455, 2024). "However, the role of USP54 in prostate cancer (PCa), especially castration-resistant prostate cancer (CRPC), remains unknown." (PMID 38321455, 2024). "We hypothesize that USP54 may influence AR signaling activity in PCa cells by deubiquitinating a protein key to AR signaling activation, However, the specific substrate of USP54 in prostate cancer remains unidentified, necessitating further research." (PMID 38321455, 2024).
sarcopenia (1 paper, 2025). Progressive decline in muscle mass due to aging which results in decreased functional capacity of muscles. "Experimental validation confirmed significant upregulation of USP54, CHAD, and ZDBF2 in aging muscles, and functional analysis revealed enrichment of signaling pathways related to bone development, immune response, and apoptosis, consistent with known mechanisms of sarcopenia." (PMID 41303670, 2025).
visual disorders (1 paper, 2016). "It is also worth noting that Usp45, Usp53 and Usp54 did show layer specificity, as they were mainly expressed in the photoreceptors (PhR inner segment, ONL and OPL), suggesting a specific role for these genes in photoreceptors and underscoring their role as potential candidates for visual disorders." (PMID 26934049, 2016).
Wilms tumor (1 paper, 2016). An embryonal neoplasm characterized by the presence of epithelial, mesenchymal, and blastema components. "USP54 is a ubiquitin-specific peptidase that activates the TNFα-NF-κB pathway, and the upregulation of this gene family has been linked to both lung and pancreatic cancers, as well as to Wilms' tumors." (PMID 26527318, 2016).
tumor (7 papers, 2016 to 2026). "Furthermore, the relapsed tumor acquired two relapse-specific mutations in USP54 and NCOR2." (PMID 26527318, 2016). "At the single-cell level, USP54 was upregulated along the trajectory of malignant ductal cells and correlated with an inflamed tumor microenvironment." (PMID 41929495, 2026). "We also found a significant mutational enrichment within the tumor-associated transmembrane signal transduction genes KRAS, PTPN21, and USP54 of relapsed patients." (PMID 26527318, 2016). "At the time of diagnosis, the tumor cells had four distinct SNVs in USP54, GABRA3, KRAS and SETD2, while the relapsed tumor acquired four additional unique mutations in MYH7, NYNRIN, ODZ1 and ZIC3." (PMID 26527318, 2016). "Spatial transcriptomics validated the co-localization of USP54 expression, elevated DUB activity, and KRAS signaling within specific tumor niches adjacent to THBS1-enriched immune regions." (PMID 41929495, 2026). "This immune-derived signaling potentially converged on KLF5-positive tumor cells, with KLF5 identified as a putative transcriptional activator of USP54." (PMID 41929495, 2026). "In the female-specific panel, genes related to aberrant androgen signaling across tumor types like androgen receptor, PLXNA1, USP54, and PMEPA1 were influential." (PMID 42137503, 2026). "Expression of ZRANB1 and USP54 was decreased in the GBM group compared to the AS and non-tumor groups." (PMID 37892185, 2023). "Lastly, in the young.tumor versus old.tumor contrast, we identified five DEGs (ZIC2, ZIC5, ZNF439, USP54, and C2); this contrast may reflect differences in intrinsic tumor properties between tumors from the two age cohorts." (PMID 28027300, 2016).
cancer (5 papers, 2016 to 2025). A tumor composed of atypical neoplastic, often pleomorphic cells that invade other tissues. "USP54 deficiency and its impact on cell viability and gefitinib response were evaluated in 2D and 3D spheroid cancer models." (PMID 40168312, 2025). "To further investigate the in vivo function of USP54 in cancer, we have generated mutant mice deficient for this DUB." (PMID 27769071, 2016). "To further evaluate the role of USP54 in cancer, we generated a mouse model deficient for this DUB by using a knockout-first (KF) strategy." (PMID 27769071, 2016). "In this regard, future studies will be required to clarify the molecular mechanisms underlying the pro-tumoral effect of USP54 in cancer progression demonstrated in this work and to explore the translatability of these findings into clinical benefits for cancer patients." (PMID 27769071, 2016). "Studies involving USP54-deficient mouse models have also shown a lower incidence of invasive adenocarcinoma but a higher incidence of dysplasia, further emphasizing USP54’s complex role in cancer." (PMID 40168312, 2025). "Collectively, this work has uncovered the pro-tumorigenic properties of USP54, highlighting the importance of deubiquitinating enzymes as promising targets for the development of specific anti-cancer therapies." (PMID 27769071, 2016). "While the significance of USP54 in tumorigenesis is known, its specific function in cancer progression remains unclear." (PMID 40168312, 2025). "USP54, a ubiquitin-specific protease in the deubiquitinase (DUB) family, facilitates the malignant progression of several types of cancer." (PMID 38321455, 2024). "However, the roles of USP54 in other cancers, especially PCa, remain unclear." (PMID 38321455, 2024). "Although the significance of USP54 in tumorigenesis has been established, its precise function as a DUB in cancer progression remains unclear." (PMID 40168312, 2025). "This suggests that USP54, while nonessential in normal physiology, plays a significant role in cancer progression and therapy resistance." (PMID 40168312, 2025).
adenocarcinoma (1 paper, 2016). A common cancer characterized by the presence of malignant glandular cells. "All wild-type animals, but only 75% of Usp54-deficient mice, developed adenocarcinomas." (PMID 27769071, 2016).
USP54 also shares sentences with these, for which no sentence is quoted: glioma (2 papers); non-small cell lung carcinoma (2); cholestasis (1); colorectal adenoma (1); endometrial carcinoma (1); lung adenocarcinoma (1); pancreatic ductal adenocarcinoma (1); viral infection (1).